AQP2 (aquaporin 2)
Diseases named in the same sentence as AQP2 in open-access papers (continued):
Sharing a sentence is not in itself a finding about the gene and the disease.
Hypokalemia (continued). "In our case, the gradual decrease in urine volume occurred only after serum potassium levels exceeded 2.0 mmol/L, supporting the hypothesis that correcting hypokalemia restored AQP2 responsiveness to ADH." (PMID 40625516, 2025). "Autophagic degradation of AQP2 is involved in both hypokalemia and hypercalcemia-induced NDI." (PMID 34884753, 2021). "Prolonged hypokalemia induces a decrease of urinary concentrating ability via down-regulation of aquaporin 2 (AQP2); however, the precise mechanisms remain unknown." (PMID 30816234, 2019). "As the amount of total- and pS261-AQP2 was decreased in K+-depleted Atg7f/f and, to a greater degree, in Atg7Δpc mice, we postulated that AQP2 might be excreted into the urinary space by exosome secretion in hypokalemia." (PMID 30816234, 2019). "Thus, enhanced autophagic degradation of proteins, most notably including AQP2, is an early event in hypokalemia-induced NDI." (PMID 26674602, 2015). "Indeed hypokalemia is known to induce polydipsia and urinary concentration defect by downregulation of aquaporin-2." (PMID 25112827, 2014). "The rat with hypercalcemia and hypokalemia had vasopressin-resistant polyuria in urinary concentrating ability and increased prostaglandin production, there were decreased adenylate cyclase and cAMP (the second messenger for vasopressin action), resulting in decrease in AQP2 expression." (PMID 34903939, 2021). "However, even though these droplets are formed in a classical rodent model of hypokalemia induced by ingestion of K+ free diet for a period of 2 weeks, it is not certain whether they comprise autophagic vacuoles or are involved in AQP2 degradation." (PMID 30816234, 2019). "Several animal models of acquired NDI including hypokalemia, hypercalcemia, ureteral obstruction, chloroquine and lithium nephrotoxicity have decreased AQP2 expression in the inner medulla; hence the need to understand the transcriptional regulation of the AQP2 gene." (PMID 25006961, 2014). "In hypokalemia‐induced NDI, AQP2 downregulation is suggested to result from reduction in apical labeling of pS256‐AQP2 and degradation of total AQP2 and p261‐AQP2 in autophagosomes." (PMID 34762363, 2021). "Notably, downregulation of AQP2 by canonical autophagic degradation in hypokalemia is not the results of an unspecific downregulation of proteins." (PMID 30816234, 2019). "The presence of AQP2 in autophagosomes and autophagolysosomes in the IMCD of potassium-deprived rats supports the role of autophagic protein degradation as the mechanism responsible for the down-regulation of IMCD proteins in the early stage of hypokalemia-induced NDI." (PMID 26674602, 2015). "Interestingly, SNX27 protein abundance was significantly decreased in the kidney inner medulla of rats with lithium-induced NDI, suggesting that autophagy could, at least in part, be involved in the downregulation of AQP2 in NDI, as demonstrated in the hypokalemia or hypercalcemia model." (PMID 32413996, 2020).
chronic kidney disease (15 papers, 2010 to 2025). Impairment of the renal function secondary to chronic kidney damage persisting for three or more months. "One of the three children was identified with the mutation of AQP2 until developing into stage 3 chronic kidney disease (CKD) at 14 years old." (PMID 33996673, 2021). "In 5/6 nephrectomy rat models (a model of chronic kidney disease), the administration of goreisan was shown to decrease aquaporin-2 expression in the kidneys." (PMID 39768446, 2024). "Animal studies have demonstrated that compared to healthy control animals, aquaporin-2 water channels (AQP2) and various sodium transporters are differentially expressed in rats with chronic renal failure (CRF)." (PMID 24970686, 2014). "Patients in the early stages of chronic kidney disease are usually asymptomatic but may experience weakness related to anemia and polyuria, suggestive of the reduced Aqp2 gene expression in the early stages." (PMID 35685285, 2022). "In general, expression level of aquaporin-2 decreases in patients with chronic kidney disease." (PMID 26784173, 2016). "AQP2 also acts as a downstream effector of inflammation; for example, the Nod-like receptor protein 3 (NLRP3)-induced inflammatory response can decrease AQP2 expression in chronic kidney disease (CKD)." (PMID 35386692, 2022). "Thus, the TGFβ-suppressed Aqp2 gene expression could account for polyuria experienced by patients in the early stages of chronic kidney disease." (PMID 35685285, 2022). "Therefore, urine aquaporin-2 could be a novel predictor to estimate the responders to tolvaptan especially among those with chronic kidney disease." (PMID 26784173, 2016). "Although several studies have shown that release of water channel proteins, aquaporin 1 (AQP1) and AQP2 in urinary extracellular vesicles (uEV‐AQP1 and ‐AQP2), were altered in experimental kidney injury models, their release in human chronic kidney disease (CKD) has been largely unexplored." (PMID 34435473, 2021). "Our results suggest that the abnormal urine dilution capacity in chronic kidney disease stage III and IV is due to a lower ability of the principal cell in the distal part of the nephron to down regulate the expression of the AQP2 water channels and in that way promote water excretion." (PMID 20923561, 2010). "However, not all patients with chronic kidney disease have reduced urine excretion of aquaporin-2." (PMID 26784173, 2016).
heart failure (15 papers, 2008 to 2024). Inability of the heart to pump blood at an adequate rate to meet tissue metabolic requirements. "The inhibition of the translocation of AQP2 into the plasma membrane may be an approach to reduce edema in heart failure where elevated levels of AVP cause a predominant localization of AQP2 in the plasma membrane of the renal principal cells." (PMID 35054947, 2022). "We here validated aquaporin-2-guided tolvaptan therapy in patients with decompensated heart failure." (PMID 26784173, 2016). "Since upregulation of AQP2 was observed in other states of arterial underfilling, namely cirrhosis and cardiac failure, it was extremely important to measure AQP2 expression in pregnancy." (PMID 24803942, 2014). "In addition, the pharmacological effect of tolvaptan can be monitored by urinary AQP2 levels in heart failure, hepatic cirrhosis and SIADH." (PMID 34884753, 2021). "In patients with heart failure, administration of a V2 receptor antagonist produced a significant increase in urine flow and solute-free water excretion, accompanied with a drastic reduction in urinary AQP2 excretion." (PMID 34884753, 2021). "Urinary AQP2 excretion is also increased in patients with heart failure, hepatic cirrhosis." (PMID 34884753, 2021). "However, recent studies of heart failure in rat models revealed increased AQP2 protein abundance even in the presence of normal AVP and unchanged plasma sodium levels." (PMID 26903868, 2016). "Heart failure experimentally induced by left coronary artery ligation in rats showed that there was marked increase in AQP2 mRNA expression and a redistribution of AQP2 in the collecting ducts with increased targeting to the apical membrane." (PMID 20142913, 2008). "Thus in heart failure AQP2 may be up-regulated more generally than previously thought." (PMID 26903868, 2016). "In another experimental model involving saline-loaded rats (a heart failure model), goreisan administration did not alter the expression of the vasopressin type 2 receptor but did reduce the expression of aquaporin-2 and -3." (PMID 39768446, 2024). "Lütken confirmed that AT1 receptor inhibitor cambishtan could reduce the expression of AQP-2 in kidneys of mice with heart failure, suggesting that RAS may play a role in regulating the expression of AQP-2 in kidneys of mice." (PMID 30809535, 2019). "In humans with heart failure and in several animal models of heart failure, RAAS system activity, the non-osmotic release of AVP and the expression level and membrane localization of AQP2 are significantly increased." (PMID 26903868, 2016).
congestive heart failure (14 papers, 2012 to 2024). Failure of the heart to pump a sufficient amount of blood to meet the needs of the body tissues, resulting in tissue congestion and edema. "Conversely, AQP2 overexpression associated with congestive heart failure, and pregnancy, leads to water retention and increased extracellular fluid volume." (PMID 23258995, 2012). "In the recent clinical literature, both urine cyclic AMP and urine aquaporin-2 levels decreased following goreisan administration in patients with congestive heart failure." (PMID 39768446, 2024). "Scientific studies appeared to be destined to clarify their roles, as well as the relationship between AQP2 and AVRP2 underlying water balance abnormalities (such as liver cirrhosis and congestive heart failure)." (PMID 34903939, 2021). "AQP2 mRNA and protein abundance were both significantly increased in the kidneys of chronic heart failure rats." (PMID 29088071, 2017). "Increases in AQP2 mRNA expression and protein abundance were found in experimental models of congestive heart failure in rats." (PMID 29088071, 2017). "We examined plasma AVP levels and urinary excretion of AQP2 in 65 patients with congestive heart failure." (PMID 26239456, 2015). "Two groups of investigators have shown an increase in AQP2 protein abundance in rats with congestive heart failure." (PMID 26239456, 2015). "Urinary excretion of AQP2 increased in the patients with congestive heart failure with higher NYHA class, and also had a significant positive correlation with plasma AVP levels." (PMID 26239456, 2015). "AQP2 is the most important aquaporin, and plays a critical role in chronic heart failure and some diseases." (PMID 26074997, 2015). "AQP2 mRNA and protein abundance were both significantly increased in the kidneys of the rats with chronic heart failure." (PMID 26239456, 2015). "Therefore, AQP2 impairment is an important cause of water retention that exacerbates the prognosis of congestive heart failure, which is now attracting considerable attention as a novel therapeutic target for water balance disorders which commonly occur in CHF." (PMID 26074997, 2015).
Hypertension (13 papers, 2013 to 2025). The presence of chronic increased pressure in the systemic arterial system. "Renal aquaporin-2 (AQP2) is critical for maintaining water balance and is associated with hypertension." (PMID 23737873, 2013). "The reduced AQP2 in the renal medulla was reported earlier in the clipped kidney of rats with experimental two-kidney, one clip hypertension and in Milan hypertensive rats." (PMID 28105926, 2016). "A significantly increased expression of Aqp2 mRNA has been observed in the kidneys of rats with spontaneous hypertension." (PMID 23737873, 2013). "These analyses are likely to advance our understanding of the regulation of AQP2 by ACE inhibitors in hypertension." (PMID 23737873, 2013). "Thus, both the higher hyaluronidase activity levels and the increased AQP2 urinary shedding indicate that in men with a family history of hypertension, the kidneys’ ability to excrete water in response to an oral load is reduced and/or impaired." (PMID 38982989, 2024). "The increase in AQP2 activity promotes water reabsorption, which may contribute to glucocorticoid-induced water retention and hypertension." (PMID 26578982, 2015). "Additionally, the increased expression of aquaporin 2 (AQP2) in these mice suggests a role in enhancing water reabsorption, further contributing to the observed high blood pressure." (PMID 39595187, 2024). "At 10 weeks of age in male SHR, an up-regulation of AQP2 channels was found in the collecting duct leading to an increased absorption of water and circulating volume expansion, suggesting that the ADH V2 receptor antagonism can attenuate arterial hypertension development." (PMID 35722114, 2022).
diabetic nephropathy (12 papers, 2010 to 2025). "Our results are in agreement with a previous small study of patients with diabetic nephropathy, in whom a decrease in u-AQP2 was associated with impaired urinary concentrating ability." (PMID 20923561, 2010). "ADCuh may work as useful metrics for early detection of kidney damage in diabetic nephropathy and may be associated with AQP-2 expression." (PMID 29708187, 2017). "Upregulation of AQP-2 and -5 is closely related to the progression of diabetic nephropathy in diabetic patients and are good candidates to use for diagnosis." (PMID 33663503, 2021). "In the patients with diabetic nephropathy, AQP5 colocalizes with AQP2 in the perinuclear region and AQP5 expression is associated with impaired cellular H3 dimethyl K79." (PMID 23326416, 2013). "Two previous studies have compared u-AQP2 in patients with CKD and diabetic nephropathy to healthy controls." (PMID 24970686, 2014). "Additional research has examined the quantities of aquaporin 5 (AQP5) and AQP2 exosome-expelled in urine in 35 diabetic patients, indicating that exosomal AQP5 and AQP2 could serve as potential noninvasive biomarkers for the classification of diabetic nephropathy (DN) clinical stages." (PMID 40305328, 2025).
Hypercalcemia (11 papers, 2014 to 2025). An abnormally increased calcium concentration in the blood. "Drug-induced hypercalcemia/hypercalciuria causes polyuria and reduces AQP2 expression in rats." (PMID 34884753, 2021). "Dihydrotachysterol-induced hypercalcemia models exhibited polyuria and decreased AQP2 expression." (PMID 39609591, 2024). "The role of hypercalcemia in AKI is multifaceted and includes hyposthenuria through the downregulation of aquaporin 2 channels and tubulointerstitial injury mediated by medullary calcium deposition." (PMID 36843787, 2023).
Cirrhosis (10 papers, 2008 to 2021). A chronic disorder of the liver in which liver tissue becomes scarred and is partially replaced by regenerative nodules and fibrotic tissue resulting in loss of liver function. "The inhibitory effect of the AAM on the AQP2 water channel in an in vitro model of excess salt concentration suggests a possible approach for cirrhosis treatment." (PMID 23258995, 2012). "Moreover, a cirrhosis risk score consisting of SNPs in 7 genes (AP3S2, AQP2, AZIN1, DEGS1, STXBP5L, TLR4, and TRPM5) has been shown to predict fibrosis progression in HCV infected patients." (PMID 26950933, 2016). "However, compensated cirrhosis induced by ligation of the common bile duct resulted in decreased AQP2 expression and consequently, V2 receptor antagonists were not effective." (PMID 20142913, 2008). "Cirrhosis is another condition with variable AQP2 expression." (PMID 20142913, 2008). "Thus, the downregulation of AQP2 observed in milder forms of cirrhosis may represent a compensatory mechanism to prevent development of water retention." (PMID 23258995, 2012). "In contrast, the increased levels of vasopressin seen in severe “noncompensated” cirrhosis with ascites may induce inappropriate upregulation of AQP2 that in turn is involved in the development of water retention." (PMID 23258995, 2012).
Polydipsia (10 papers, 2014 to 2025). Excessive thirst manifested by excessive fluid intake. "Ten boys from nine families were identified with mutations in AVPR2 or AQP2 along with dehydration, polyuria–polydipsia, and severe hypernatremia." (PMID 33996673, 2021). "The downregulation of AQP2 in the inner medulla (~ 60%) accounts for the significant polyuria and polydipsia along with reduced urine osmolality exhibited by rats fed 2500 mg/kg adenine." (PMID 40794384, 2025). "In contrast to the originally stated hypothesis, none of the abnormalities that are characteristic of our murine model of lithium‐induced NDI that is, polydipsia, polyuria, hypoosmotic urine, and reduced renal AQP2 mRNA and protein expression, were beneficially altered by sPRR‐His treatment." (PMID 29138356, 2017).
Sepsis (10 papers, 2012 to 2024). Sepsis is defined as life-threatening organ dysfunction caused by a dysregulated host response to infection. "Pretreatment with a continuous erythropoietin receptor activator (CERA) or α-lipoic acid has been demonstrated to preserve Aqp2 expression and protect against sepsis-induced AKI." (PMID 39544938, 2024). "Sepsis-induced dysregulation of AQP2 can impair water reabsorption, potentially leading to fluid imbalances and worsening renal function." (PMID 39768394, 2024). "We analyzed the urinary expression of the renal transporters Na+/H+ exchanger (NHE3), collector duct sodium channel (ENaC), renal outer medullary potassium channel (ROMK), and aquaporin-2 (AQP2) in patients exposed to sepsis and ischemia." (PMID 37675036, 2022). "Another study has reported that downregulation of AQP2 expression in lipopolysaccharide-induced AKI participated in urinary concentration defect in sepsis." (PMID 30654539, 2019). "Pretreatment of rats with continuous erythropoietin receptor activator (CERA) preserves Aqp2 expression in rat kidneys and protects against sepsis induced AKI." (PMID 29449936, 2018). "The downregulation of Aqp2 in sepsis models is confirmed by animal models using LPS induced endotoxemia after short time exposure (6 h), whereas after long time exposure (18 h) Aqp2 expression is increased in kidney." (PMID 29449936, 2018). "This study reported miR-34b-5p as a novel biomarker in septic AKI patients, which could regulate sepsis-induced renal injury by inhibiting AQP2." (PMID 39768394, 2024). "Finally, dysregulated vasopressin and angiotensin II levels in sepsis influence AQP2 in the kidney, impacting urine concentration and contributing to AKI." (PMID 39768394, 2024). "Notably, downregulation of AQP2 and sepsis-induced AKI progression were alleviated by reduced activation of nuclear factor kappa B (NF-κB) signaling pathways." (PMID 39768394, 2024). "Moreover, AQP1 and AQP2 upregulation by various molecules in the setting of sepsis-induced AKI has been shown to suppress the disease’s development." (PMID 38203657, 2023). "Regarding AQP2, studies show that its expression is downregulated in lipopolysaccharide (LPS)-induced AKI, contributing to impaired urinary concentration during sepsis." (PMID 39768394, 2024). "n a porcine model of sepsis-induced AKI, treatment with human umbilical cord-derived mesenchymal stem cells (hUC-MSCs) resulted in a reduction in the expression of Aqp2 in the renal medulla, indicating a protective effect on renal function." (PMID 39544938, 2024). "Conversely, the authors showed that NF-κB inhibition ameliorates sepsis-induced AKI in the CLP model, which is in agreement with our finding that pre-CLP administration of CERA maintained normal expression of AQP2 and NKCC2." (PMID 22235348, 2012). "It has been shown that the expression of AQP2 and NKCC2 in the renal outer medulla is downregulated in rats with lipopolysaccharide-induced sepsis." (PMID 22235348, 2012).